PPME1 (protein phosphatase methylesterase 1)
Description:
Demethylates proteins that have been reversibly carboxymethylated. Demethylates PPP2CB (in vitro) and PPP2CA. Binding to PPP2CA displaces the manganese ion and inactivates the enzyme.
Synonyms: PME-1; ABDH19
Tractability: Small molecule: a high-quality ligand is known; it belongs to a druggable protein family. PROTAC: ubiquitination databases record sites on it; its protein half-life has been measured; a small molecule that binds it is known.
Target class: Enzyme; Hydrolase
Chemical probes: ABL127 (high quality), AMZ30
Gene: Protein-coding gene on chromosome 11 (74,171,083 to 74,254,703, forward strand). Ensembl gene ENSG00000214517.
Subcellular location (Human Protein Atlas): Nucleoplasm; Nuclear bodies
Pathways (Reactome):
Cell Cycle: Cyclin A/B1/B2 associated events during G2/M transition
Gene Ontology:
Molecular function: cadherin binding; protein binding; protein methylesterase activity; protein phosphatase 2A binding; protein phosphatase binding; protein phosphatase inhibitor activity; lncRNA binding; protein kinase binding
Biological process: G2/M transition of mitotic cell cycle
Cellular component: nuclear body; nucleoplasm
Genetic constraint (gnomAD): Loss-of-function variants: 9 observed, 34.84 expected, observed/expected ratio (o/e) 0.26, 90% interval 0.16 to 0.45. The synonymous counts are far from expectation, so gnomAD's model fits this gene poorly and the ratio says little. Missense variants: 297 observed, 390.62 expected, observed/expected ratio (o/e) 0.76, 90% interval 0.69 to 0.84. Synonymous variants: 98 observed, 129.37 expected, observed/expected ratio (o/e) 0.76, 90% interval 0.64 to 0.9.
Homologues: Orthologues: chimpanzee PPME1 (100% identical), macaque PPME1 (100% identical), rabbit PPME1 (99% identical), pig PPME1 (99% identical), mouse Ppme1 (98% identical), guinea pig PPME1 (98% identical), rat Ppme1 (98% identical), dog PPME1 (96% identical), tropical clawed frog ppme1 (86% identical), zebrafish ppme1 (76% identical), Drosophila melanogaster CG5068 (49% identical), Caenorhabditis elegans B0464.9 (42% identical).
Diseases named in the same sentence as PPME1 in open-access papers:
PPME1 is named in the same sentence as 32 diseases in open-access papers, as found by Europe PMC text mining. Sharing a sentence is not in itself a finding about the gene and the disease. The quoted sentences say what the papers report.
pancreatic carcinoma (3 papers, 2021 to 2022). "For instance, lncRNA DNAH17-AS1 upregulates PPME1 expression through decoying miR-432-5p to promote pancreatic carcinoma cell proliferation, migration and invasion." (PMID 35039872, 2022).
breast carcinoma (2 papers, 2021 to 2026). "To substantiate our findings, we evaluated PPME1 expression and protein levels in breast cancer tissues through RT-qPCR, Western blotting, and immunohistochemical techniques." (PMID 41884849, 2026). "In breast cancer, PPME1 mRNA and protein levels are elevated in tumor tissues compared to adjacent normal tissue." (PMID 41884849, 2026).
lung carcinoma (2 papers, 2015 to 2019). "Additionally, a small fraction (3–4%) of the gastric and lung cancer patients shows PPME1 gene amplification, which also corresponds to elevated PME‐1 protein expression and activation of ERK and AKT survival signaling." (PMID 26377365, 2015). "Analogously, genes involved in wound healing and cell migration (i.e., SERPINE1, HMGCR, IGFBP5, and S100A14) or reported as prognostic factors in breast, ovarian, gastric, and lung cancers (i.e., MAPRE1, HSPA1B, and PPME1) were negatively modulated." (PMID 31752957, 2019).
thyroid cancer (2 papers, 2022 to 2024). "Similarly, lncRNA HOTAIR upregulates PPME1 to impact thyroid cancer cell behaviors through miR-761 competition." (PMID 35443670, 2022). "HOTAIR promotes proliferation and inhibits apoptosis of thyroid cancer cell lines (HTh-7, CAL-62, BCPAP) by silencing the expression of protein phosphatase methylesterase 1 (PPME1) by miR-761 sponging." (PMID 38339237, 2024).
dengue (1 paper, 2025). "B7, Bacillus licheniformis, and Clostridium cochlearium, along with the host genes, namely, PPME1, TIMP2, NLRC4, and RhoB, were associated with immune dysregulation in the severe dengue patients." (PMID 41417796, 2025).
heart failure (1 paper, 2024). Inability of the heart to pump blood at an adequate rate to meet tissue metabolic requirements. "The distinct expression patterns of Ppme1, Sec31a, and Gm56451 in MI and TAC highlight their potential as biomarkers for different types of heart failure." (PMID 39502510, 2024). "Notably, Ppme1, Gm56451, and Sec31a showed contradictory expression patterns between MI and TAC, suggesting their potential as biomarkers for MI- and TAC-induced heart failure, respectively." (PMID 39502510, 2024).
rectum adenocarcinoma (1 paper, 2015). An adenocarcinoma arising from the rectum. "Analysis of PPME‐1 mRNA expression from TCGA dataset of colon and rectal adenocarcinoma (COADREAD) patient cohort confirmed high PPME1 expression as an independent protective factor predicting favorable overall survival (OS) (P = 0.005, n = 396) compared to patients with low PPME1 expression." (PMID 26377365, 2015).
cancer (14 papers, 2015 to 2026). A tumor composed of atypical neoplastic, often pleomorphic cells that invade other tissues. "Elevated levels of PPME1 constitute an independent risk factor in various cancers, including BLCA, BRCA, HNSC, KICH, LIHC, and UVM, and are associated with a poor prognosis." (PMID 41884849, 2026). "Ppme1, known to inactivate PP2A, a tumor suppressor, has been implicated in various cancers through the promotion of oncogenic MAP kinase and Akt pathways." (PMID 39502510, 2024). "Protein phosphatase methylesterase-1 (PME-1) is the sole PP2Ac methylesterase, and the higher PME-1 expression is observed in various cancer and neurodegenerative diseases." (PMID 38588804, 2024). "Its protein product, protein phosphatase methylesterase 1, is regarded as a key molecule that sustains the activation of ERK activity in cancer cells via inhibition of PP2A." (PMID 26810418, 2016). "Interestingly, PPME1, a gene previously linked to the HGPS-mutated gene lamin A (LMNA), was significantly altered in both HGPS and the neurodegenerative disorders PD and AD, but not in the cancer disease PM." (PMID 32811487, 2020).
tumor (13 papers, 2015 to 2026). "These upshots approved that hsa_circ_0050102 lack repressed xenograft tumour growth via miR‐218‐5p/PPME1 axis in vivo." (PMID 35060203, 2022). "We also found that Rbb7, Pkn1, and Ppme1 are overexpressed in the middle area of the tumor compared to its center and periphery." (PMID 36151122, 2022). "In the opposite direction, we found that the gene Ppme1 is significantly underexpressed in the 4T1 tumor center compared to tumor middle and tumor periphery." (PMID 36151122, 2022). "Compared with the unconverted CD44-/CD24- tumor cells, PPME1, RHBDL2 and HIST1H4H mRNA transcripts increased in the newly converted CD44+/CD24- CSCs with a change of >two folds, which were similar to that in parental CD44+/CD24- CSCs." (PMID 34318746, 2021). "Protein phosphatase methylesterase-1 (PME-1), a regulator of the tumor suppressive phosphatase PP2A, promotes PP2A demethylation and inactivation, and is overexpressed in 44% of GBM, associated with increased tumor grade and cellular proliferation." (PMID 37500619, 2023).
PPME1 also shares sentences with these, for which no sentence is quoted: glioma (5 papers); infection (3); Alzheimer disease (2); Cognitive impairment (2); glioblastoma (2); malignant glioma (2); neuroblastoma (2); neurodegenerative disease (2); progressive supranuclear palsy (2); prostate carcinoma (2); tauopathies (2); cervical cancer (1); choriocarcinoma (1); colon cancer (1); colorectal cancer (1); dementia with Lewy bodies (1); endometrial cancer (1); Fusarium infection (1); liver cancer (1); lung adenocarcinoma (1); lung disease (1); neurological disorders (1); rectal cancer (1).